MIR376A1 (microRNA 376a-1)
Synonyms: hsa-mir-376a; hsa-mir-376a-1; MIR376A-1; MIRN376A; MIRN376A-1; MIRN376A1; mir-376a-1
Gene: MicroRNA gene on chromosome 14 (101,040,782 to 101,040,849, forward strand). Ensembl gene ENSG00000283588.
Homologues: Orthologues: rabbit MIR376A1 (100% identical).